FNDC5 (fibronectin type III domain containing 5)
Diseases named in the same sentence as FNDC5 in open-access papers (continued):
Sharing a sentence is not in itself a finding about the gene and the disease.
Obesity (continued). "Indeed, the reduced muscle expression of FNDC5, which is dependent on PGC-1α, has been associated with various pathological conditions, such as heart failure and obesity, suggesting the potential to counteract disorders of different origins through ERRs activation." (PMID 40692696, 2025). "Rb1 may ameliorate obesity in part through the MSTN/FNDC5 signalling pathway." (PMID 35639355, 2022). "However, obesity increased Fndc5 expression compared with the aged lean mice." (PMID 36296923, 2022). "However, the molecular link, if existing, between GLP-1 and FNDC5 for executing anti-obesity actions remains unknown." (PMID 34869379, 2021). "However, it is unclear whether FNDC5 is involved in cardiac fatty acid oxidation during obesity, and the crosstalk between PPAR-α and JAK2/STAT3 signaling or other signal transduction molecules needs further investigation." (PMID 30940158, 2019). "However, this was seen in both control and Atg7h&mKO mice, which is not consistent with a preferential contribution of Fndc5 to the more pronounced obesity-resistant phenotype caused by exercise training in autophagy deficient mice." (PMID 28801668, 2017). "We realized that the anti-obesity effects of GLP-1 and GLP-1RAs notably overlap with those of FNDC5/irisin." (PMID 34869379, 2021). "In Fndc5-/- mice, HFD induced more pronounced body weight gain, suggesting that Fndc5 knockout partly deteriorated the HFD-induced obesity." (PMID 33754067, 2021). "In humans, the synthesis of FNDC5 and secretion of IR are higher in the skeletal muscles of people with obesity but without T2DM, probably to maximize GL uptake by muscles and prevent hyperglycemia." (PMID 36615169, 2023). "Fibronectin type III domain-containing protein 5 (FNDC5), a novel myokine secreted by contracting skeletal muscle, can attenuate inflammation and insulin resistance through AMPK-mediated macrophage polarization in HFD-induced obesity." (PMID 32646451, 2020). "Moreover, irisin’s precursor, fibronectin type III domain-containing protein 5 (FNDC5), is decreased in patients with obesity." (PMID 30261060, 2018). "Here, we summarize three candidate myokines (IL-6, FNDC5 and MSTN); we speculate that they may exert effects on the recruitment and polarization of macrophages in adipose tissue, thus regulating inflammation states in obesity." (PMID 35273574, 2022). "Here, the aim of this study is to evaluate the role and molecular mechanism of FNDC5 on cardiac function, inflammatory and oxidative stress responses in HFD-induced obese mice, which would be used for future therapeutic interventions in obesity-related complications." (PMID 30940158, 2019). "FNDC5/irisin seems to act in an autocrine/paracrine fashion, as an adipokine, to stimulate browning once its skeletal muscle secretion correlates with insulin resistance in diet-induced obesity, but does not influence the adipocyte plasticity towards a thermogenic phenotype." (PMID 29351550, 2018).
Insulin resistance (42 papers, 2013 to 2025). Increased resistance towards insulin, that is, diminished effectiveness of insulin in reducing blood glucose levels. "⁃ Palmitate-induced insulin resistance is linked to the loss of myotubes and the low expression of myonectin, FNDC5, and FGF21." (PMID 40741175, 2025). "FNDC5 gene deficiency aggravated fat accumulation, obesity, insulin resistance, and inflammation accompanied with enhanced AMPK inhibition, macrophages recruitment, and M1 polarization." (PMID 31736870, 2019). "Previous studies reported the strong association between FNDC5/irisin and insulin resistance estimated by homeostatic model assessment, and by testing glucose tolerance." (PMID 30388754, 2018). "Serum irisin levels and single nucleotide polymorphisms in the FNDC5 are associated with glucose metabolism and insulin resistance." (PMID 30388754, 2018). "In summary, palmitate-induced insulin resistance is associated with myotube loss and impaired expression of three health benefit myokine genes (FNDC5, CTRP15 and FGF21) in C2C12 myotubes." (PMID 23866690, 2013). "Palmitate-induced insulin resistance accompanys myotube loss and the impaired expression of FNDC5, CTRP15 and FGF21genes in C2C12 myotubes." (PMID 23866690, 2013). "Here, we assessed whether common single nucleotide polymorphisms (SNPs) in the FNDC5 locus, encoding the irisin precursor, contribute to human prediabetic phenotypes (overweight, glucose intolerance, insulin resistance, impaired insulin release)." (PMID 23637927, 2013). "It was demonstrated that NAD+-boosting therapy can upregulate FNDC5/Irisin, resulting in positive outcomes like reduced body weight gain, improved hepatic steatosis, insulin resistance, and decreased mitochondrial dysfunction and fibrosis." (PMID 39594505, 2024). "Eight weeks of AE significantly reduced body weight, increased the serum FNDC5 level, and improved the homeostatic model assessment of insulin resistance." (PMID 36982812, 2023). "Studies have shown that the irisin precursor protein FNDC5 attenuates inflammation and insulin resistance in adipose tissue through the AMPK-mediated polarization of obese macrophages." (PMID 36062149, 2022). "Mice overexpressing FNDC5 exhibited protection from high fat diet (HFD) diet-induced insulin resistance." (PMID 35563026, 2022). "Next, we investigated the influence of Fndc5 knockout on the improvement of NR against HFD-induced insulin resistance." (PMID 33754067, 2021). "Since mitochondrial dysfunction precedes insulin resistance and steatosis 56, we measured the expression of genes involved in mitochondrial biogenesis and mitophagy in WT and Fndc5-/- mice." (PMID 33754067, 2021). "A recent study evaluated the effects of exercise on the PGC-1α/FNDC5/irisin pathway using different models of Alzheimer’s disease, which is considered a type 3 diabetes due to the presence of insulin resistance in the brain, in mice." (PMID 33672171, 2021). "Their findings showed that Fndc5 plays a critical role in attenuating adipose tissue inflammation and insulin resistance." (PMID 32257109, 2020). "The excess FFA activates the TGF-β signaling pathway to induce insulin resistance through Smad-3-mediated downregulation of the Fndc5 gene." (PMID 33060792, 2020). "Downregulation of FNDC5 expression resulted in the increase of steatosis and in insulin resistance and higher apoptosis of primary hepatocytes to TNF-α." (PMID 33198247, 2020). "In obese mice, overexpression of Fndc5 or subcutaneous administration with recombinant irisin reduces hyperglycemia, hyperlipidemia, and improves insulin resistance." (PMID 33379163, 2020). "Our previous studies showed the beneficial roles of FNDC5 in attenuating the disturbance of glucose and lipid metabolism, insulin resistance, and hepatosteatosis." (PMID 32509148, 2020). "FNDC5 attenuates the disturbance of glucose and lipid metabolism, insulin resistance, and hepatosteatosis." (PMID 32509148, 2020).
Insulin resistance (continued). "Together, these studies add value to the potential of FNDC5/irisin as an effective strategy in attenuating metabolic dysregulation and insulin resistance in obesity and T2D." (PMID 31635130, 2019). "We postulate that insulin resistance stimulates activation of the PGC‐1a/FNDC5 pathway as a compensatory response in effort to increase insulin sensitivity and attenuate impaired insulin signaling." (PMID 28676551, 2017). "Hypomethylation is typically associated with increased gene expression, suggesting that the elevated Fndc5 expression may lead to dysregulation of insulin sensitivity pathways and contribute to insulin resistance." (PMID 41509541, 2025). "There is a strong correlation between FNDC5/irisin and insulin resistance." (PMID 40660735, 2025). "In addition, using adenoviral overexpression of FNDC5, the same study had reported that Irisin increases total body energy expenditure and protects against obesity-induced insulin resistance in mice." (PMID 35563026, 2022). "This is the first experiment that reveals that FNDC5/irisin can improve insulin resistance." (PMID 35627690, 2022). "Fibronectin type III domain containing 5 (FNDC5) is known to attenuate insulin resistance, and improves glucose and lipid metabolism 56-58, while increased miR-135a-5p in the EVs of SHR promotes VSMCs proliferation via inhibiting FNDC5 expression in WKY and SHR 26,59." (PMID 35832088, 2022). "In HFD-induced NAFLD mice model, NR displayed remarkable therapeutic effects on body weight gain, hepatic steatosis, steatohepatitis, insulin resistance, mitochondrial dysfunction, apoptosis and fibrosis; however, these actions of NR were compromised in Fndc5-/- mice." (PMID 33754067, 2021). "It is known that FNDC5 attenuates insulin resistance and glucose and lipid metabolism disorders." (PMID 34440213, 2021). "In relation to glucose metabolism, although it was shown that irisin is able to ameliorate general glucose metabolism, we did not observe any change on insulin sensitivity when performing an insulin resistance experiment (High glucose/high insulin) with FNDC5-KO adipocytes." (PMID 29176631, 2017). "Considering the role that activation of the PGC‐1α‐FNDC5/irisin pathway may have in response to insulin resistance, Pearson correlations were performed between FNDC5 protein levels in muscle or adipose and body weight, fasting blood glucose, and HOMA‐IR." (PMID 28676551, 2017). "Also, high-fat diets could increase the expression of Zfp57 by inhibiting the AMPK pathway, thereby inducing the inhibition of FNDC5 and further exacerbating insulin resistance in mouse muscle cells." (PMID 38405155, 2024). "In mice fed a high-fat diet (HFD), the overexpression of FNDC5 increased the serum levels of irisin, slightly reduced the weight, and, most prominently, improved hyperglycemia and hyperinsulinemia, suggesting an improvement in the insulin resistance of the mice." (PMID 35392577, 2021). "We propose that PGC‐1α‐FNDC5/irisin pathway may be upregulated as a compensatory mechanism to induce browning of adipose and subsequently increase energy expenditure to oppose increased adiposity and insulin resistance." (PMID 28676551, 2017). "Irisin plays a role in reducing insulin resistance and glucose homeostasis in AD subjects, and stimulation of fibronectin type III domain-containing protein 5 (FNDC5)/irisin by endurance exercise has been reported." (PMID 37600508, 2023). "Other studies also showed that FNDC5 overexpression in obese mice induced with HFD increases energy expenditure, attenuates hyperglycemia and insulin resistance, and activates lipolysis in adipose tissues." (PMID 33790964, 2021). "FGF19 treatment restored PA‐ and HFD‐induced hyperglycaemia, impaired glucose tolerance and insulin resistance (IRS‐1, GLUT‐4) and mitigated the PA‐ and HFD‐induced decrease in FNDC‐5/irisin expression." (PMID 33751819, 2021).
Insulin resistance (continued). "Here, we report increased FNDC5 and PGC‐1α protein in skeletal muscle and adipose in HF sedentary mice that exhibit increased bodyweight, fasting glucose, insulin, HOMA‐IR and cellular insulin resistance as measured by decreased Akt activation." (PMID 28676551, 2017). "The serine phosphorylation of IRS-1 (Ser-307 and Ser-636 sites), which counteracted IRS-1 tyrosine phosphorylation and contributed to insulin resistance 53, was enhanced by HFD but suppressed by NR in WT mice but not in Fndc5-/- mice." (PMID 33754067, 2021). "Induction of insulin resistance by treating cells with a combination of high glucose and high insulin (HGHI) showed that cells lacking FNDC5 are not more resistant to insulin than control cells after 10 minutes insulin stimulation." (PMID 29176631, 2017).
Alzheimer disease (39 papers, 2018 to 2025). A progressive, neurodegenerative disease characterized by loss of function and death of nerve cells in several areas of the brain leading to loss of cognitive function such as memory and language. "It was demonstrated that irisin rescues synaptic plasticity alongside the FNDC5 protein, which is associated with neuroplasticity, in an exercise-linked manner on Alzheimer’s disease mouse models." (PMID 41019298, 2025). "Exercise-induced myokine FNDC5/irisin have been shown to be protective against cardiovascular damage post ischemic event, improve function in the neurons of Alzheimer’s disease patients, and have been implicated in macrophage and adipocyte regulation." (PMID 30984367, 2019). "Analysis of Alzheimer disease (AD) patients and accompanying studies utilizing AD animal models also linked exercise-induced FNDC5/irisin to improved synaptic plasticity in symptomatic patients and animals." (PMID 30984367, 2019). "We thus analysed data from 240 cognitively unimpaired (CU) and 485 cognitively impaired (CI) participants from the Alzheimer’s Disease Neuroimaging Initiative (ADNI) cohort to investigate if SNPs within the FNDC5 gene are associated with changes in FDG-PET, cognition and AD biomarkers." (PMID 37601408, 2023). "FNDC5/irisin levels are reduced in the hippocampi of patients with Alzheimer’s disease (AD) and in experimental models, with evidence suggesting that increasing these levels can restore synaptic plasticity and improve memory." (PMID 41321034, 2025). "FNDC5/irisin has been detected in the hippocampus to affect synaptic plasticity in Alzheimer's disease." (PMID 39698584, 2024). "Findings from 2019 described the role of FNDC5 in regulating synaptic function and memory in mouse models of Alzheimer’s disease and of irisin in activating the canonical Notch signalling pathway to exert its neuroprotective effects." (PMID 37766686, 2023). "Our results indicate that a genetic variant of FNDC5 is associated with low brain glucose metabolism in elderly individuals and suggest that FNDC5 may participate in the regulation of brain metabolism in brain regions vulnerable to Alzheimer’s disease pathophysiology." (PMID 37601408, 2023). "Lourenco and colleagues made a significant discovery, noting reduced levels of FNDC5 in the brains of human Alzheimer's Disease, cerebrospinal fluid, and AD mouse models." (PMID 38260156, 2023). "Permanent PEs accomplished as daily swimming restore the impaired levels of FNDC5/irisin in blood in the animal’s models of Alzheimer’s disease." (PMID 36776770, 2022). "Several new investigations have given evidence for the protective role of Fndc5/irisin in Alzheimer's disease 37, pulmonary ischemia injury 38, bone remodeling 39 and hepatic steatosis." (PMID 33754067, 2021). "In neuronal culture, elevating the levels of FNDC5 was found to reverse the apoptotic effects of Ab1−42 oligomers in Alzheimer's disease (AD) model and counteracts the suppression of BDNF expression by them." (PMID 34018309, 2021). "In Alzheimer’s disease (AD) for example, FNDC5 expression is decreased not only in the hippocampus but also in prefrontal cortex." (PMID 33935687, 2021). "Reduced levels of FNDC5/irisin in the brain and cerebrospinal fluid in patients with Alzheimer’s disease further support the implication of such defective signaling in humans." (PMID 31083472, 2019). "Accordingly, physical exercise-induced cognitive improvement together with increased neurogenesis and BDNF, FNDC5 levels, and synaptic proteins in the hippocampus of 5XFAD transgenic mice, a model for Alzheimer’s disease." (PMID 31083472, 2019). "Additionally, we chose FNDC5, a precursor of irisin, which plays a crucial role in metabolic functions and has shown reduced expression levels in Alzheimer’s disease." (PMID 38139046, 2023).
Alzheimer disease (continued). "FNDC5 and irisin have been detected in the brain, and irisin has been shown to mediate the beneficial actions of physical exercise in mouse models of Alzheimer’s disease (AD)." (PMID 36187295, 2022). "In addition, FNDC5 can stimulate transient activation of ERK1/2 in Alzheimer’s disease mouse models." (PMID 36672836, 2022). "Molecular mediators of the benefits of exercise include muscle-derived myokine FNDC5/irisin that prevents neurodegeneration and rescues memory impairment in a model of Alzheimer’s disease, and liver-derived glycosylphosphatidylinositol-specific phospholipase D1 that improves cognition in aged mice." (PMID 33790323, 2021). "Furthermore, exercise and FNDC5/Irisin have been shown to have several neuroprotective effects against injuries in ischemia and neurodegenerative disease models, including Alzheimer’s disease." (PMID 33935687, 2021). "This led us to investigate whether FNDC5 is involved in the mechanism due to which exercise has a beneficial effect on Alzheimer’s disease, in particular, on the Aβ pathology directly." (PMID 30355327, 2018). "Similarly, FNDC5/irisin knockout mice have been shown to have reduced memory performance, while peripheral overexpression of FNDC5/irisin has been shown to improve memory impairment in a murine Alzheimer’s disease model." (PMID 30984367, 2019). "In Alzheimer’s disease rats, BDNF was found to positively regulate the secretion of FNDC5 by muscle cells, thereby improving cognitive function in these rats." (PMID 41195080, 2025). "Considering these results, FNDC5 probably plays the role of a critical mediator in the pathology of Alzheimer’s disease; however, the exact mechanism of how FNDC5 affects APP metabolism has not been referred yet." (PMID 30355327, 2018). "Intravenous administration of AdFNDC5 led to increment of both plasma and hippocampal FNDC5/irisin expression, and restored novel object recognition (NOR) memory defects in Alzheimer’s disease (AD) mice." (PMID 36267573, 2022).
diabetes (29 papers, 2013 to 2025). "The inverse regulation of FNDC5 in both sarcopenia and diabetes suggests its role as part of an adaptive mechanism to counteract mitochondrial dysfunction, particularly under conditions of muscle-wasting or metabolic stress." (PMID 40869253, 2025). "The levels of irisin, a proteolytic product of fibronectin type III domain-containing 5 (Fndc5), were shown to be lower in patients with type 2 diabetes mellitus." (PMID 37352205, 2023). "FNDC5 is the precursor of the myokine irisin proposed to exhibit favorable metabolic activity, including anti-obesity and anti-diabetes effects." (PMID 35321332, 2022). "Then we established a mouse model of diabetes with MI/R by feeding FNDC5-/- mice with high-fat diet." (PMID 33013403, 2020). "Many studies have been investigated the relationship of FNDC5 / irisin with obesity, chronic kidney disease, Type 2 Diabetes Mellitus, and chronic diseases." (PMID 32102531, 2020). "In the present study, we established a mouse model of diabetes with MI/R by feeding FNDC5-/- mice with high-fat diet." (PMID 33013403, 2020). "Irisin is produced by the proteolytic cleavage of the fibronectin type III domain-containing protein 5 (FNDC5) and plays a pivotal role in the occurrence and development of obesity, diabetes, non-alcoholic fatty liver disease, and other metabolic diseases." (PMID 30246803, 2018). "In all WAT depots studied, FNDC5 gene expression enhanced with diabetes, and these values decreased significantly (even over control values) after insulin treatment." (PMID 27432282, 2016). "The study was able to show an increase in mRNA for PGC1 α and FNDC5 after 12 weeks of physical training in both control and pre-diabetes human subjects." (PMID 25898830, 2015). "However, in individuals with diabetes, the amount of FNDC5 in muscle cells decreases by approximately 15%." (PMID 38431555, 2024). "Secondly, as our patients with diabetes were not newly diagnosed and were treated with anti-diabetic drugs and/or insulin, we cannot perform the association between the SNPs in FNDC5 and clinical parameters in patients." (PMID 25369206, 2014). "However, whether FNDC5/irisin can ameliorate diabetic osteopathy through modulating ER stress‐mediated ferroptosis remains to be further investigated." (PMID 38555440, 2024).